MTTP (microsomal triglyceride transfer protein)
Diseases named in the same sentence as MTTP in open-access papers (continued):
Sharing a sentence is not in itself a finding about the gene and the disease.
steatosis (22 papers, 2010 to 2025). Increased lipid within the cytoplasm of cells. "The conditional liver-specific HNF4α disruption in mice led to severe steatosis and reduced serum triglycerides, which were associated with the selective disruption of ApoB and MTTP genes’ expression." (PMID 36362837, 2022). "The present study also investigated the I128T SNP of the MTTP gene, and the risk of steatosis was 8.51-fold higher in patients with the IT/TT genotype of the I128T SNP when combined with HCV genotype 3 infections." (PMID 36027755, 2022). "Finally, we leveraged the APOB- and MTTP-mutant organoids to establish a CRISPR-based screening platform to identify steatosis modulators/targets and to evaluate NAFLD risk genes." (PMID 36823355, 2023). "Human fetal hepatocyte organoids model NAFLD steatosis under three triggers: fatty acid overload, PNPLA3 I148M mutation, and APOB/MTTP mutations." (PMID 40475995, 2025). "APOB−/− and MTTP−/− mutant organoids constitute a natural steatosis organ model and can be maintained in long-term culture at levels that maintain a stable level of steatosis." (PMID 37175830, 2023). "Steatosis is caused by three main triggers: overload nutritional diet, high risky variant (PNPLA3 I148M) and predisposed monogenic lipid disorders (APOB or MTTP mutation)." (PMID 37009924, 2023). "Both APOB−/− and MTTP−/− mutants constitute natural steatosis organoid models that can, like their WT counterparts, be long-term expanded in culture for at least 2 years with stable steatosis levels." (PMID 36823355, 2023). "Similar to our data, a previous study reported that MTTP-deficient patients showed impaired exports of VLDL from the liver, thereby resulting in the development of steatosis with the accumulation of triglycerides in the liver." (PMID 34681291, 2021). "Animal models of decreased hepatic MTTP activity have revealed an unexplained dissociation between hepatic steatosis and hepatic insulin resistance." (PMID 32907986, 2020). "Previous studies have shown that NAFLD patients with simple steatosis exhibit higher hepatic expression of MTTP and ApoB, as well as higher serum VLDL levels." (PMID 33187321, 2020). "Liver-specific conditional knockout of HNF4α in adult mice led to severe steatosis associated with disruption of VLDL secretion and misregulation of ApoB and MTTP expression." (PMID 31781248, 2019). "MTTP levels were downregulating in knockout mice for miR-122 suggesting that MTTP reduction by impairing TG release promotes intrahepatic accumulation contributing to steatosis and fibrosis." (PMID 30581418, 2018). "In contrast, similar expression levels of MTTP and apoB100 between patients with steatosis, NASH, and healthy controls have also been reported, denoting the considerable disease heterogeneity associated with NAFLD." (PMID 29936596, 2018). "There was a positive correlation between the histological grade of steatosis and reduction in the MTTP mRNA." (PMID 23554788, 2013). "We selected 17 candidate NAFLD drugs from recent drug development programs and from new targets reported in the literature, focusing on those with putative hepatic effects, and screened these drugs in the FFA-induced and genetic (APOB−/− and MTTP−/−) steatosis models." (PMID 36823355, 2023). "Previously established APOB−/−or MTTP−/−organoids exhibited severe steatosis phenotype, and could be passaged for long-term expansion." (PMID 37009924, 2023). "Therefore, the restoration of MTTP and ApoB mRNA levels by GSEE treatment also can also act as an inhibitory mechanism of HFD-caused steatosis." (PMID 33187321, 2020). "By the increased expression of MTTP, the development of steatosis can be slowed down." (PMID 28824430, 2017). "Of note, the isolated presence of HCV genotype 3 and the isolated presence of the MTTP mutation did not significantly increase the risk of steatosis (P = 0.080 and P = 0.116, respectively)." (PMID 28356060, 2017).
steatosis (continued). "In patients with HCV genotype 3 and mutation (GT/TT) of the MTTP gene, the risk of steatosis was 25.22-fold greater than in patients without these associated characteristics (P < 0.001)." (PMID 28356060, 2017). "In patients with HCV genotype 3 and the MTTP mutation (GT/TT), the risk of steatosis was 25.22 times higher than in patients without these associated characteristics." (PMID 28356060, 2017). "Here we use human fetal hepatocyte organoids to model the first stage of NAFLD, steatosis, representing three different triggers: free fatty acid loading, interindividual genetic variability (PNPLA3 I148M) and monogenic lipid disorders (APOB and MTTP mutations)." (PMID 36823355, 2023). "To better understand the potential role of MALAT1 silencing as a molecular determinant through which Ex-4 mediates its beneficial effect on steatosis, we quantified SREBP1, PPRAδ, FAS, SCD1, ACC, and MTTP at the protein level before and after silencing." (PMID 40002783, 2025). "For the FFA model, WT organoids were first made steatotic with a fixed concentration of FFAs (500 μM) for 3 days before drug administration, to induce a degree of steatosis similar to that observed in APOB−/− and MTTP−/− organoids." (PMID 36823355, 2023). "HCV is known to directly induce steatosis via interactions between core protein and lipogenic regulators such as SREBP-1c and microsomal triglyceride transfer protein (MTP)." (PMID 20862263, 2010). "Since AMPK is known to phosphorylate PGC1α, which also increases MTTP and ApoB expression, our results suggest that GSEE could exert its anti-steatosis effect by regulating multiple processes such as lipid export, synthesis, and consumption in mouse livers." (PMID 33187321, 2020). "In HCV-3 induced steatosis, the MTP activity and the MTTP mRNA level were both reduced." (PMID 23554788, 2013). "Using steatosis score as the readout, they scanned a panel of anti-NAFLD drugs (positive on animal models), and found inhibitors of ACC, FAS and DGAT2, a FXR agonist, as well as recombinant hFGF19 could efficiently alleviate the steatosis in FFA models and APOB−/−or MTTP−/− models." (PMID 37009924, 2023). "Likewise, hepatic mRNA levels of apoB100 and MTTP and serum VLDL-TG were higher in patients with steatosis (n = 51) compared to patients with NASH (n = 53), marking deterioration of VLDL assembly and export as important in the progression from steatosis to NASH." (PMID 29936596, 2018). "Interestingly, recent data have suggested that the polymorphism of various genes, including the PPAR-gamma, IL-28B, adiponutrin and microsomal triglyceride transfer protein (MTP) genes, may influence the development of more severe steatosis in chronic carriers of HCV." (PMID 22479436, 2012).
familial hypercholesterolemia (17 papers, 2012 to 2026). An inheritable form of hyperlipidemia, in which there are excess lipids in the blood. "Apo B-100 and Apo B-48 mutations caused by APOB100 and MTP (microsomal triglyceride transfer protein) gene defects are associated with metabolic disorders like abetalipoproteinaemia, hypobetalipoproteinemia and hypercholesterolemia." (PMID 26555091, 2016). "Lomitapide mesylate is an inhibitor of microsomal triglyceride transfer protein (MTP) used for the treatment of homozygous familial hypercholesterolemia." (PMID 36052650, 2022). "Recently, the MTTP inhibitor lomita-pide has been registered on the European and US markets for the treatment of unresponsive homozygous familial hypercholesterolemia, despite some limitations regarding its side effects." (PMID 32882484, 2020). "The MTTP inhibitor lomitapide has been approved to treat patients with homozygous familial hypercholesterolemia; however, this approach induces hepatic fat accumulation and increased plasma transaminases." (PMID 32907986, 2020). "In 2012 Lomitapide was approved as the first in class MTTP inhibitor for the treatment of family hypercholesterolemia." (PMID 30547786, 2018). "The MTTP inhibitor (lomitapide) is also approved for the treatment of inherited hyperlipidemias like homozygous familial hypercholesterolemia and familial chylomicronemia syndrome, but its usage is associated with severe side effects and therefore is not recommended for the treatment of obesity." (PMID 35437952, 2022). "The hypercholesterolemia, in the Reversa mouse, can be eliminated by inducing the expression of the Mx1-Cre transgene, which inactivates the gene for microsomal triglyceride transfer protein (Mttp) that is required for the secretion of apoB-containing lipoproteins." (PMID 22934038, 2012).
hyperlipidemia (11 papers, 2013 to 2025). "Several MTTP polymorphisms have been reported relating to metabolic syndrome, hyperlipidemia and steatohepatitis." (PMID 26458397, 2015). "Previous reports have demonstrated subjects with MTTP promoter -493G/T or I128T polymorphisms are susceptible to develop metabolic syndrome, hyperlipidemia, more oxidative stress, ischemic heart disease, β-cell dysfunction and non-alcoholic steatohepatitis." (PMID 26458397, 2015). "Hence, it might be useful to determine whether mutations in miR-30c gene(s) and/or MTTP 3 ́-UTR could cause hyperlipidemia in humans." (PMID 24007526, 2013). "C57BL6/J mice were injected with AAVmPCSK9 and were fed with Western diet for 16 weeks, followed by reversal of hyperlipidemia by a diet switch to chow and treatment with a microsomal triglyceride transfer protein inhibitor (MTPi)." (PMID 28291840, 2017). "The reversal of hyperlipidemia by inactivation of MTTP leads to regression of atherosclerosis over a few weeks accompanied by favorable changes in the composition of the atherosclerotic plaque." (PMID 25429291, 2014). "It has been suggested that pitavastatin decreases the expression of mRNA of microsomal triglyceride transfer protein (MTTP) from the liver in an animal model of postprandial hyperlipidemia." (PMID 24386561, 2013).
colorectal cancer (10 papers, 2021 to 2025). A primary or metastatic malignant neoplasm that affects the colon or rectum. "MTTP levels were found to be increased in the plasma exosomes of colorectal cancer patients with a high body fat ratio, correlating with a poor therapy response." (PMID 37895415, 2023). "Among other proteins that are transferred via exosomes is the microsomal triglyceride transfer protein (MTTP), which inhibits ferroptosis and induces resistance to oxaliplatin in colorectal cancer." (PMID 37895415, 2023). "Adipocyte‐derived exosomal MTTP inhibits ferroptosis and promotes chemoresistance to oxaliplatin in colorectal cancer through the MTTP/PRAP1/ZEB1 axis." (PMID 36253096, 2022). "A recent study revealed that MTTP protein could inhibit ferroptosis and enhance chemoresistance in colorectal cancer." (PMID 36838613, 2023). "For example, adipose tissue-derived exosomes are enriched with microsomal triglyceride transfer protein (MTTP), which can increase GPX4 expression and decrease PUFAs levels, resulting in ferroptosis inhibition and drug resistance in colorectal cancer cells." (PMID 39346540, 2024). "Their exosomal microsomal triglyceride transfer protein (MTTP) upregulates GPX4 and XCT to inhibit ferroptosis in colorectal cancer, while adipocyte-secreted oleic acid attenuates lipid peroxidation and ferroptosis in triple-negative breast cancer cells in an ACSL3-dependent manner." (PMID 40285867, 2025).
Obesity (10 papers, 2011 to 2023). Accumulation of substantial excess body fat. "For instance, microsomal triglyceride transfer protein (MMTP) gene located in HSA q24 were found as a candidate gene for obesity in humans." (PMID 23977060, 2013). "These nanovesicles target microsomal triglyceride transfer protein (MTP) and angiopoietin-like protein-4 (ANGPTL 4) in the mitochondria, which are therapeutic targets for reducing plasma lipids and inflammation in gastrointestinal diseases caused by obesity." (PMID 38001440, 2023). "Limiting MTTP inhibition to enterocytes however might represent a more promising strategy for the treatment of obesity and hyperlipidemia." (PMID 35437952, 2022). "Among the nine negatively (OR > 1) correlated SNPs, the upstream variant MT:16362T > C in the MT-TP gene (encoding microsomal triglyceride transfer protein) showed the most significant (P = 0.007; OR = 0.38) negative association with obesity." (PMID 33659027, 2021). "High fat diet-induced obesity and metabolic syndromes can also modulate the methylation pattern of various gene promoters in human and animal models, such as leptin, peroxisome proliferator activated receptor γ (PPARγ) or microsomal triglyceride transfer protein (Mttp)." (PMID 25171162, 2014). "Compound II is an inhibitor of microsomal triglyceride transfer protein (MTP) and useful for the treatment of obesity and atherosclerosis." (PMID 21915210, 2011).
dyslipidemia (9 papers, 2013 to 2025). "MTTP, which has associations with metabolic syndrome, body mass index, and insulin regulation, showed a strong signature of selection in Southeast Asians, including Indonesians." (PMID 23349834, 2013). "Targeted next-generation sequencing of genomic DNA comprised all known dyslipidemia genes, including MTTP (ABL gene), APOB (FHBL gene), PCSK9 and SAR1B (chylomicron retention disease gene)." (PMID 29540175, 2018). "Compensatory upregulation of proteins such as liver fatty acid-binding protein (L-FABP) and microsomal triglyceride transfer protein (MTTP) reflects the intestine’s attempt to manage excess lipid intake but exacerbates systemic dyslipidemia in mice long-term fed on an HFD." (PMID 40474970, 2025). "We identified a rare causal variant c.1691T>C p.I564T (rs745447480) in MTTP, encoding microsomal triglyceride transfer protein (MTP), associated with progressive NAFLD, unrelated to metabolic syndrome and without characteristic features of abetalipoproteinaemia." (PMID 37484212, 2023).
hypertriglyceridemia (7 papers, 2013 to 2021). A laboratory test result indicating elevated triglyceride concentration in the blood. "ChREBP enhances VLDL secretion in part through regulation of MTTP, and variants in the ChREBP locus are associated with hypertriglyceridemia in humans." (PMID 34684643, 2021). "MTTP inhibitors have been shown to reduce circulating VLDL and LDL in animal models and human subjects and thus are a valuable addition to the pharmacopoeia for patients with severe hypertriglyceridemia." (PMID 32907986, 2020). "Furthermore, microsomal triglyceride transfer protein (MTP) is involved in the secretion of triglyceride-rich VLDL, which leads to hypertriglyceridemia and atherosclerosis." (PMID 30119682, 2018). "Further, overexpressed LPK and MTTP mRNAs and hypertriglyceridemia were also without significant change." (PMID 23737835, 2013).
hypobetalipoproteinemia (7 papers, 2016 to 2026). A group of lipoprotein metabolism disorders that are characterized by permanently low levels (below the 5th percentile) of apolipoprotein B and LDL cholesterol. "Hepatocellular steatosis, low circulating LDL-C, and hypobetalipoproteinemia are particularly common among HCV genotype 3 (GT3) patients, due to viral-mediated inhibition of the microsomal triglyceride transfer protein." (PMID 34372608, 2021).
Insulin resistance (6 papers, 2013 to 2025). Increased resistance towards insulin, that is, diminished effectiveness of insulin in reducing blood glucose levels. "By multivariate analysis, the significant association of MTTP polymorphisms with serum triglyceride was overpowered by the impact of insulin resistance (HOMA-IR and Adipo-IR) and BMI." (PMID 26458397, 2015). "The MTTP 297H polymorphism interacted with age, insulin resistance and BMI to decrease serum apoB containing lipoproteins (LDL-C and non-HDL-C) but increase the risk of NAFLD formation." (PMID 26458397, 2015). "Based on our result, metabolic regulators such as insulin resistance or body mass index did modulate the phenotypic manifestation of MTTP polymorphisms." (PMID 26458397, 2015). "However, our results revealed genetic impact of the MTTP polymorphisms on serum triglyceride was overpowered by insulin resistance and BMI." (PMID 26458397, 2015). "Dysregulation of MTTP expression can lead to many diseases, such as lipid metabolism disorders, insulin resistance and cardiovascular diseases." (PMID 40213543, 2025). "Studies have shown that in animal models of diabetes or insulin resistance, the MTTP mRNA expression and activity in the intestine are increased, and the content of triglycerides in chylomicrons are increased." (PMID 34443619, 2021). "To better understand the effects of MTTP ablation over time, we studied both young and aged liver-specific MTTP knockout mice (L-Mttp−/−), assessing the development of lipid-induced hepatic insulin resistance." (PMID 32907986, 2020).
type 2 diabetes (6 papers, 2012 to 2024). "Finally, the nonsynonymous SNP rs3816873 in the MTTP gene (iHS = 2.43, P = 0.015) was found to significantly associate with lower levels of insulin, blood pressure, and prevalence of type II diabetes in a European population." (PMID 36026493, 2022). "Minor allele carriers of rs756998920 were not susceptible to type 2 diabetes (not shown), but further genetic studies are required to reveal whether heterozygotes for the functionally disrupting allele of MTTP have altered plasma TG levels and NAFLD risk." (PMID 28950858, 2017).
hepatoma (5 papers, 2017 to 2025). "Fresh garlic extract reduced microsomal triglyceride transfer protein (MTP) mRNA levels in both human hepatoma HepG2 and intestinal carcinoma Caco-2 cells." (PMID 36430776, 2022). "The endogenous MTTP gene was ablated in human hepatoma Huh-7 cells using single guide RNA and RNA-guided clustered regularly interspaced short palindromic repeats-associated sequence 9 ribonucleoprotein complexes." (PMID 35931202, 2022). "We hypothesized that ablation of the MTTP gene in human hepatoma cells might avoid the need to transfect large plasmids expressing human apoB100." (PMID 35931202, 2022). "Therefore, we hypothesized that knockout of the endogenous MTTP gene in hepatoma cells may avoid the need to transfect cells with large apoB100 expressing plasmids for secretion studies." (PMID 35931202, 2022).